IL1B (interleukin 1 beta)
Diseases named in the same sentence as IL1B in open-access papers (continued):
Sharing a sentence is not in itself a finding about the gene and the disease.
neurodegenerative disease (continued). "Taken in context with our findings, neuropathology and chronically upregulated IL-1β may act additively or even synergistically to incapacitate the steady-state vesicle flow throughout the cell and impair neuronal function in various neurodegenerative diseases." (PMID 28153028, 2017). "However, by examining the consequences of a cerebral IL-1β challenge we may facilitate our understanding of the role of this cytokine in neurodegenerative disease and disorder." (PMID 26989349, 2016). "Therefore, the investigation of the regulatory or modulatory mechanisms for brain maturation and release of IL-1β may provide therapeutic clues for neuroinflammatory/neurodegenerative diseases." (PMID 23940760, 2013). "Elevated IL-1β, IL-18, and inflammasome proteins such as ASC and caspase-1 have been reported in neurodegenerative disease and TBI, often correlating with severity or outcome." (PMID 41511361, 2026). "IL-6 and IL-1β are also documented in supporting SC activation in PNI and other neurodegenerative diseases." (PMID 40160208, 2025). "Assembly of the NLRP3 inflammasome further promotes activation of caspase-1, IL-1β, and IL-18, which are key contributors to neurodegenerative pathology and further support the role of the TLR/ NFκB/NLRP3 axis in neurodegenerative disease." (PMID 40507859, 2025). "NF-κB and MAPKs (JNK, ERK, and p38) signaling pathways are pivotal transcription factors for microglial activation and production of cytokines such as IL-1β, IL-6, and TNF-α in various neurodegenerative diseases." (PMID 39764462, 2024). "After TBI, microglia was quickly activated and released various inflammatory mediators, including TNF-α, IL-1B, IL6, NO and ROS, which have been proved to be related in some neurodegenerative diseases." (PMID 36869312, 2023). "In some neurodegenerative diseases, TGF-β1 stimulates the production of inflammatory cytokines such as IL-1β and TNF-via phosphorylation of Smad proteins, including Smad2 and Smad3, in rat neurons." (PMID 37240885, 2023). "We performed RT-PCR to determine the changes in the mRNA expression of pro-inflammatory markers interleukin-1β (IL-1β), tumor necrosis factor-α (TNF-α), interleukin-6 (IL-6), and iNOS based on their potential involvement in neurodegenerative diseases." (PMID 37816735, 2023). "Thrombin induces the expression of proinflammatory cytokines such as NO, IL‐1β, IL‐6, and TNF‐α by activating PAR, promoting inflammation, and driving the progression of neurodegenerative diseases." (PMID 37654024, 2023). "In neurodegenerative diseases, amyloid proteins trigger NLRP3 inflammasome, leading to activation of CASP1 and release of IL-1β." (PMID 37578928, 2023). "Inflammatory cytokines have been confirmed to mediate reactive astrocyte proliferation in neurodegenerative diseases, such as TNF-α and IL-1β." (PMID 35506163, 2022). "In pathological conditions of neurodegenerative diseases, iron overload triggers microglial polarization to the pro-inflammatory (M1) phenotype via ROS, which increases the secretion of TNF-α and IL-1β and promotes neuroinflammation." (PMID 35342364, 2022). "The expression of IL‐1β, IL‐6, TNF‐α, and iNOS is harmfully correlated with the development of neurodegenerative diseases." (PMID 33942523, 2021). "Researchers have found that patients with neurodegenerative disease display higher concentrations of IL-6,TNF-α, IL-1β, and NF-κB." (PMID 34944391, 2021). "In an in-vitro model of neurodegenerative disease, it was confirmed that pro-inflammatory cytokines interleukin-1β (IL-1β) and TNF are elevated in the neurodegenerative disease state and induced neuronal death and apoptosis." (PMID 34877406, 2021). "IL-1β has been shown to negatively regulate BDNF-dependent learning and memory in neurodegenerative diseases." (PMID 31948437, 2020). "Proinflammatory cytokines such as TNFα, IL1β, IL-6, and COX2 play an important role in the pathological process of neurodegenerative diseases." (PMID 32560481, 2020).
neurodegenerative disease (continued). "Cartilage degenerative diseases have an inflammatory component involving increased expression of pro-inflammatory factors such as TNF-α, IL-1β, and IL-6." (PMID 31666429, 2019). "The expression levels of IL-1β, TNFα, COX2, and iNOS are detrimentally related to the progression of neurodegenerative diseases." (PMID 31883536, 2019). "However, our results show that there is a substantial increase in the levels of P-parkin in IL-1β-treated neurons (p < 0.001), suggesting that a kinase other than PINK1 can phosphorylate parkin and may do so in conditions, such as those in neurodegenerative diseases, where IL-1β levels are elevated." (PMID 31882005, 2019). "Increasing evidence has demonstrated that microglial activation and the consequent release of proinflammatory and cytotoxic factors such as TNFα, IL-1β, NO, and prostaglandin E synthase 2 (PGE2) are thought to contribute to the neurodegenerative diseases." (PMID 24349614, 2013). "IL-1β and TNF-α are two of the inflammatory cytokines significantly elevated in neurodegenerative diseases such as AD, and they play a central role in initiating and regulating the cytokine cascades during inflammatory responses." (PMID 24455696, 2013). "Thus, COX-2, iNOS and MMP-9 activities, as well as TNFα, IL-1β and NO generation have become accepted as markers and therapeutic targets in neurodegenerative diseases, and thus their down-regulation might assist in preventing or delaying the onset of these diseases." (PMID 22018032, 2011). "Pro-inflammatory cytokines such as IL-1β and TNF-α play an important role in mediating neuronal death and neuroinflammation in various neurodegenerative diseases." (PMID 21034511, 2010). "IL-1β also plays a dual role in IBDs and neurodegenerative diseases, and no conclusion has been drawn." (PMID 38891863, 2024). "Furthermore, pro-inflammatory cytokines such as IL-1β and TNF-α have been identified as major contributors to synaptic and neuronal pathology in fatal neurodegenerative diseases such as EAE and MS." (PMID 39766497, 2024). "Furthermore, increased expression of proinflammatory cytokines such as IL-6, IL-1β, and TNFα that we detected in IFNγ treated SPG11 iMGL, was also described for iPSC-derived microglia from patients with other neurodegenerative diseases, including PD and ALS." (PMID 38305941, 2024). "The BBB is responsible for protecting the central nervous system (CNS) from the peripheral immune system; however, in many neurodegenerative diseases, such as AD, the integrity of the BBB is compromised by cytokines released by inflammation in the CNS, including TNF-α, IL-6, and IL-1β." (PMID 37323140, 2023). "Astrocytes may contribute to inflammation by serving as an inducible source of inflammatory cytokines, such as IL1β, TNFα, and IL6; these cytokines have been demonstrated to be involved in neurodegenerative diseases, including ALS pathogenesis." (PMID 36046683, 2022). "Conversely, inflammation has been increasingly demonstrated to contribute to the development of degenerative changes in the CNS, whereas subsequent increases in the levels of inflammatory cytokines, such as IL-1β and TNF-α, have been proposed to be pathological drivers of neurodegenerative diseases." (PMID 33805302, 2021). "After 5 to 8 days, labeled astrocytes were treated or not for 24h with IL-1β, an inflammatory mediator shown to be upregulated in the context of multiple conditions such as brain injury, neurodegenerative diseases and infections." (PMID 33968073, 2021). "OA is not entirely a degenerative disease, being partly an inflammatory condition involving the actions of IL-1β, IL-6, and nitrotyrosine." (PMID 34855756, 2021). "Cytokines, including TNF-α and IL-1β, have been shown to mediate reactive astrogliosis, which is reflected by the expression of glial fibrillary acidic protein (GFAP) and cell migration, in neurodegenerative diseases." (PMID 31185608, 2019).
neurodegenerative disease (continued). "One is to attenuate the inflammatory response through cytokine regulation, and several previous experiments showed that the IL-1β and TNF-α signaling pathways could be inhibited to benefit neurons in neurodegenerative diseases." (PMID 29382106, 2018). "The cleavage and maturation of IL-1β are activated by NLRP3 inflammasome, and the activation of NLRP3 inflammasome can contribute to pathophysiological processes involved in diabetic complications and neurodegenerative diseases." (PMID 29507694, 2018). "Several studies have shown that aging is accompanied by an increase in the production of pro-inflammatory cytokines, such as IL-6, IL-1β, and TNF-α, which promote chronic inflammation in the elderly and favor the onset and progression of degenerative diseases that are common in this period." (PMID 29232896, 2017). "Taken together, the literature and our data suggest that IL-1β-induced impairment of BDNF-dependent Erk5 action may contribute to the deleterious role of inflammation in aging and neurodegenerative diseases." (PMID 28153028, 2017). "This kind of regulation reflects the powerful biological activity of IL-1β that, if not properly controlled, can be at the basis of numerous inflammatory and degenerative diseases (Dinarello, 2011a,b)." (PMID 28642703, 2017). "For example, the activation of astrocytes results in the production of diverse pro-inflammatory cytokines, such as IL-1β, TNF-α and IL-6, which may be a first step in the development of several neurodegenerative disease." (PMID 26729092, 2015). "It is becoming increasingly apparent that OA is not simply a degenerative disease, but a multifactorial inflammatory disease involving a host of inflammatory mediators, including IL-1β, IL-6 and NO." (PMID 26083352, 2015). "Interleukin-1β (IL-1β), TNF-α and IL-6 are secreted in reactive astrocytes, which may be a first step in the development of several neurodegenerative diseases." (PMID 26729092, 2015). "Cell stimulation with α-synuclein, a neurodegenerative disease-related peptide, did not result in the release of active IL-1β by microglia, despite a weak pro-inflammatory effect." (PMID 26091541, 2015). "Besides NO, excessive production of inflammatory mediators such as proinflammatory cytokines including interleukin-1 beta (IL-1β) and tumor necrosis factor (TNF) from activated microglia contributes to uncontrolled inflammation in neurodegenerative diseases." (PMID 26047814, 2015). "It is well documented that microglia have been recognized as gatekeepers of CNS diseases and immunology and that microglial cells activated by LPS, by hypoxia, or by neurodegenerative diseases produce increased amounts of proinflammatory cytokines such as TNF-α and IL-1β in the CNS." (PMID 21310085, 2011). "We chose to measure changes in the mRNA expression of interleukin-1β (IL-1β), tumor necrosis factor-α (TNF-α), Fas, interleukin-6 (IL-6), leukemia inhibitory factor (LIF), and interferon γ (IFN-γ) based on their potential involvement in neurodegenerative diseases." (PMID 33628191, 2021). "Since IL-1β accumulation is an invariant feature across many neurodegenerative diseases, our study suggest that compromised BDNF retrograde transport-dependent signaling may have important implications in neurodegenerative diseases." (PMID 28153028, 2017). "Strength training for 6-12 weeks did not alter plasma IL-1β, IL-2, IL-6 and TNF-α concentration in healthy elderly adults and patients with chronic-degenerative diseases, while 12 weeks of resistance training decreased muscle TNF-α mRNA in frail elderly individuals." (PMID 33936044, 2021). "IL1R1 is expressed by NSCs of the dentate gyrus but not the SVZ and IL-1β decreases hippocampal NSC proliferation, via activation of NFkB signaling and elevated levels of IL-1β are observed in the brains of patients suffering neurodegenerative diseases." (PMID 27143977, 2016).
metabolic disorders (129 papers, 2012 to 2026). "IL-10 and IL-1β are pleiotropic cytokines with multiple biological effects linked to metabolic disorders." (PMID 38674931, 2024). "Dairy cows supplemented with Sacchromyces cerevisiae had higher levels of IL-1β in plasma, greater milk yield, and reduced risk of metabolic disease." (PMID 38004631, 2023). "Activation of IL-1β has been associated with a high inflammatory environment in some vital organs such as adipose tissue and pancreatic beta cells, resulting in metabolic disorders." (PMID 37953818, 2023). "Other inflammasomes and molecules related to the activation cascade (e.g., CARD8, AIM2, IFI16, CASP-1, and IL-1β) have also been found to be associated with a variety of infections and metabolic diseases." (PMID 36105941, 2022). "Inflammatory reactions are triggered by the production of pro-inflammatory cytokines such as TNF-α IL-1β, and IL-6 which are linked in the development of a number of metabolic diseases." (PMID 36552644, 2022). "The inherited metabolic disease PXE has previously been shown to involve aberrant gene expressions associated with the inflammatory IL-1β pathway." (PMID 35740472, 2022). "Circulating serum levels of pro-inflammatory mediators, such as interleukin (IL)-1β, IL-6, tumor necrosis factor-α, C-reactive protein, and matrix metalloproteinases, are associated with both PD and lipoprotein disorders in elderly individuals." (PMID 33138320, 2020). "Although the NLRP3 inflammasome is essential for host defense during infections, uncontrolled activation and overproduction of IL-1β and IL-18 increase the risk of developing autoimmune and metabolic disorders." (PMID 33101288, 2020). "Overall, our findings implicate a role for monocyte derived IL-1β as a potential mechanism in the increased risk for IR and metabolic disease among PLWHA." (PMID 33028018, 2020). "Next, we assessed levels of cytokines (TNF-α, IL-1β, and IL-6) that have been implicated in both metabolic disease and AD pathogenesis." (PMID 32993686, 2020). "The present study provided new evidence to show the direct contribution of NLRP3 inflammasome in the pathogenesis of DCM, which was associated with the IL-1β-related metabolic disorder and caspase-1-mediated pyroptosis in myocardium." (PMID 25136835, 2014). "NLRP3 inflammasome formation promotes the proximity-induced autocatalytic activation of caspase-1 and mediates the cleavage/activation and secretion/release of the pro-inflammatory cytokines IL-1β and IL-18 implicated in several metabolic disorders." (PMID 23924318, 2013). "The IL-1β-511 C/T variant, involved in inflammatory pathways, and Apo B-100 2488 C/T, a marker in lipid metabolism, have been scrutinized for their associations with inflammatory diseases and metabolic disorders, respectively." (PMID 39202588, 2024). "In this clinical context, the pharmacological blockade of TLR4 or the NLRP3/IL-1β/IL-1 receptor axis may provide a therapeutic strategy for preventing and/or treating the vascular alterations associated to metabolic diseases." (PMID 32214150, 2020). "Furthermore, NLRP3 inflammasome-mediated IL-1β has been identified as a key pathogenic cytokine that triggers and/or promotes various metabolic disorders." (PMID 30717382, 2019). "Given the role IL-1β plays in perpetuating chronic inflammation in metabolic disorders and that circadian disruption further enhances susceptibility to these disorders, our findings may identify BMAL1 as a critical regulator of this glucose metabolism-inflammation feedback loop." (PMID 34858390, 2021). "The aggravation of oxidative stress not only stimulates the release of IFN-γ from macrophages, but also induces the secretion of inflammatory factors such as IL-6 and IL-1β, ultimately leading to metabolic disorders in the intestinal mucosa." (PMID 40284675, 2025). "Key cytokines involved include TNF‐α, IL‐6, and IL‐1β, which are pivotal in the interplay between metabolic disease, inflammation, and carcinogenesis." (PMID 40661794, 2025).
metabolic disorders (continued). "Inflammatory signaling pathways (such as JNK and IKK) and inflammatory cytokines (such as TNF-a and IL-1b) have been reported to be involved in the pathogenesis of metabolic diseases." (PMID 37762143, 2023). "Many studies have shown that pro-inflammatory cytokines and chemokines such as TNF-α, IL-6, MCP-1, and IL-1β in the liver play key roles in the progression of metabolic diseases." (PMID 36676939, 2022). "As a transcription factor, NF-κB plays a critical role in various inflammatory-associated metabolic diseases, and its activation induces the production of proinflammatory cytokines TNF-α, IL-1β and IL-6." (PMID 36139325, 2022). "The degeneration of chondrocytes is a vital part of the progression of OA, and inflammatory elements such as IL-1β and TNF-α are regarded as the main cause of chondrocyte metabolic disorders." (PMID 35800437, 2022). "Collectively, our results indicate that Vangl2 silencing protects chondrocyte from IL-1β-induced metabolic disorder in vitro." (PMID 33588909, 2021). "PPARδ contributes to anti-inflammation and anti-apoptosis effects and suppresses cellular migration in metabolic diseases by inhibiting IL1β." (PMID 33318871, 2021). "The production of ceramide in the liver increased the secretion of cytokines such as IL-6, TNF-α, and IL-1β, which should contribute to enhancing inflammatory responses in metabolic diseases." (PMID 32547402, 2020). "Chronic inflammation is an important pathogenic factor in metabolic diseases, and macrophages regulate inflammation by producing proinflammatory cytokines including tumor necrosis factor-alpha (TNF-α) and interleukin-1 beta (IL-1β)." (PMID 32443660, 2020). "Diverse reports have suggested that metabolic diseases are associated with chronic inflammation, in which NLRP3 inflammasome activation and IL-1β and IL-18 cytokine production have been implicated." (PMID 29151018, 2017). "In fact, a number of systematic reviews have shown the association between inflammatory biomarkers, such as CRP, IL-1β, IL-6, TNF-α, IL-4, or IL-10, and cardio-metabolic diseases." (PMID 27527152, 2016). "Inflammasome activation leads to maturation of caspase-1 and processing of IL1β, contributing to many metabolic disorders and directing adipocytes to a more insulin-resistant phenotype." (PMID 27321128, 2016). "IL-1β is a proinflammatory protein involved in metabolic disorders and produced by monocytes and macrophages activated in the form of inactive protein (pro-IL-1β)." (PMID 25324698, 2014). "NLRP3 inflammasome-mediated production of mature IL-1β has been recently identified as a critical mediator in the disease progression of a variety of metabolic diseases." (PMID 25192391, 2014). "Conversely, IL-1β is considered an instigator of metabolic disease due to its capacity to drive sterile inflammation." (PMID 23984304, 2013). "Extensive studies in humans and animal have found that IL-1β, or inflammasome components required for the secretion of IL-1β, are increased in metabolic disease (reviewed in Refs." (PMID 23984304, 2013). "In particular, increased levels of cytokines such as TNF-α, IL-1β and IL-17 are present in both HS and metabolic disorders, supporting this hypothesis." (PMID 40217596, 2025). "LPS is a major factor in bacterial pathogenesis and can cause a series of inflammatory responses in the body, including the release of inflammatory factors such as TNFα, IL1β and IL6, causing a variety of inflammatory symptoms such as metabolic disorders, fever and circulatory disturbances." (PMID 38504633, 2024). "In general, ghrelin inhibits metabolic disorders and the apoptosis of NP cells by inhibiting the IL‐1β‐induced NK‐κB signalling pathway and stimulates the anabolic metabolism of NP cells by activating the AKT signalling pathway, thus providing a protective effect on IVD." (PMID 37661635, 2023). "However, excessive exposure to IL-1β can occur and exacerbate autoinflammatory diseases and metabolic disorders." (PMID 36904006, 2023).